BMP2 (bone morphogenetic protein 2)
Diseases named in the same sentence as BMP2 in open-access papers (continued):
Sharing a sentence is not in itself a finding about the gene and the disease.
tumor (continued). "In contrast, BMP-2 and -4 are strongly expressed in the surrounding mesenchymal cells, irrespective of weak expression in tumor cells." (PMID 36415832, 2022). "Based on the information currently available in the literature, BMP-2 is believed to be mainly secreted by cells in the tumor microenvironment, but not the breast cancer tumor cells themselves." (PMID 34983451, 2022). "Thus targeting BMP2/4 in an in vivo PDX model of SMAD4(-) EAC cells decreases chemoresistance and induces tumor cell death." (PMID 35902550, 2022). "The expression levels of BMP-2/4 and ALK3 were upregulated in tumor tissues." (PMID 35693928, 2022). "We found that BMP2, BMP4 and SHH were highly expressed in tumor, lung and colon." (PMID 35902550, 2022). "Gremlin-1 transcripts are found in various different tumor types and can functionally interfere with the TGF-β (transforming growth factor-beta) signaling pathway by the inhibition of the bone morphogenetic proteins BMP2 and BMP4." (PMID 34072967, 2021). "Bone morphogenetic protein 2 (BMP-2) was observed to be weakly positive in the tumor cells in the metastatic lymph node, the luminal membrane of the primary tumor, and adjacent normal mucosa; the primary tumor was judged to be negative for BMP-2." (PMID 33388078, 2021). "BMP-2 treatment activates the Hippo kinase cascade, which includes mammalian Ste20-like kinase 1 (MST1), MOB kinase activator 1 (MOB1), and YAP (inactivation), and this action is tumor suppressive." (PMID 32731498, 2020). "In the absence of BMP-2, the tumor showed a small area of osteogenic differentiation that just surrounded the ceramic material; however, when BMP-2 was added to the ceramic-fibrin structure, the OS-like tumor occupied a much larger area." (PMID 29386041, 2018). "We have previously demonstrated that exogenous BMP-2 administration did not increase local tumor recurrence rates with a xenograft murine model." (PMID 28264040, 2017). "Three-dimensional spheroid BME cell invasion assay with and without the addition of BMP2 demonstrated no qualitative differences in invasion across all tested tumor lines." (PMID 28264040, 2017). "We report de‐repression of Bmp2 and Bmp7 in Angptl2−/− ISEMFs and decreased accumulation of β‐catenin in Angptl2−/− mouse crypts, suggesting that ANGPTL2 may function as a tumor promotor in intestine." (PMID 28043948, 2017). "Wang and colleagues reported that BMP-2 treated severe combined immunodeficiency (SCID) mice did not develop tumors following heterotopic tumor implantation." (PMID 28264040, 2017). "Previous experiments have demonstrated that the addition of exogenous BMP-2 does not increase the rate of local tumor recurrence." (PMID 28264040, 2017). "Furthermore, different BMP ligands such as BMP2, BMP4, BMP6 and BMP7 induce angiogenesis, and BMP2 and BMP4 promote tumor angiogenesis." (PMID 27977771, 2016). "Neutralization of BMP2 and BMP4 in mice inhibited xenografted tumor growth induced by Dragon." (PMID 26029998, 2015). "Similarly, bone morphogenetic proteins (BMPs)— BMP2, BMP4, and BMP7, and all-trans RA have been shown to inhibit tumor initiation by promoting astorglial and neuronal differentiation in GBM cells." (PMID 26307681, 2015). "BMP2 and BMP4 are less expressed in tumor cells, osteoblast-like cells and stromal cells." (PMID 25529855, 2014). "In this study, we observed that the mRNA expression of BMP-2 in tumor tissue was significantly higher than in matched adjacent normal tissues (P < 0.01)." (PMID 24946687, 2014). "We evaluated the expression of BMP-2 mRNA using quantitative real time RT-PCR, and explored the relationship between BMP-2 mRNA levels and TNM stage, node status, gender, age, differentiation, and tumor stage." (PMID 24946687, 2014). "Interestingly, bone morphogenetic protein 2 (BMP-2) is an important and powerful tumour suppressor in the colon and is thus an attractive candidate protein for delivery through genetically modified bacteria." (PMID 22315590, 2012).
tumor (continued). "Moreover, our results point to discrete differences in high oxygen and BMP2 sensitivity between GBM cells and normal cells that should be exploited to better define tumor cell biology." (PMID 19587783, 2009). "However, beyond quiescence, we observed that BMP activation by BMP2/7 in a H3.3K27M epigenetic context induces a transcriptomic switch rather than conferring enhanced invasion potential to pDMG tumor cells." (PMID 39373720, 2024). "Our results show that BMPRII is strongly bound to BMPRI following treatment with BMP-2, but this interaction was completely abolished in the presence of TrkB, but not by the TrkB KD mutant, indicating that TrkB kinase activity is required for it to interfere with BMP-mediated tumor suppression." (PMID 32731498, 2020). "Nevertheless, this concern remains highly disputed, and there is evidence that BMP-2 may serve as driver of tumor cell differentiation rather than proliferation." (PMID 28264040, 2017). "The absence of NF1 in MPNSTs may lead to increased secretion of BMP2 that promotes malignant characteristics within the tumor microenvironment." (PMID 27494873, 2016). "Regarding enriched functions for these gene patterns, Tumor-like functions included AP-1 transcription factor network, COX reactions or activation of AP-1, whereas Adjacent-specific functions were enriched in axon guidance, PPAR signaling pathway or BMP2 signaling pathway, among others." (PMID 24597571, 2014). "Importantly, in normal SVZ cells, chemically HIF-1α stabilization was only transiently inducing REDD1 upregulation and Akt/mTOR pathway was not inhibited, unlike in tumor cells, following BMP2 treatment, and Akt and Stat3 were eventually upregulated." (PMID 19587783, 2009). "However, recent studies demonstrate that HER2+ tumor cells can acquire an osteoblastic phenotype, actively producing hydroxyapatite crystals through activation of epithelial-mesenchymal transition (EMT) and the expression of genes such as BMP-2, RUNX2, and osteopontin." (PMID 40725750, 2025). "Moreover, we only studied the dosage and carriers of rhBMP2 that could lead BMP2 to be released into the blood; whether locally delivered rhBMP2 without blood release could promote the growth of ectopic tumor could not be speculated." (PMID 32195173, 2020). "However, in the presence of extracellular signaling molecules that can induce Id1 but not GCIP expression in NSCLC cell lines (e.g., BMP2), upregulation of Id1 may overcome the tumor suppressive functions of GCIP." (PMID 24970809, 2014). "More particularly, BMP signaling (non-canonical) is triggered by the overexpressed BMP2 and 4, promoting EAC (SMAD4-negative) aggressiveness; however, the inhibition of BMP2/4 via the VHHs limits tumor growth and increases survival." (PMID 41369383, 2025). "While the reduction of the BMP-Smad1/5/8 axis is in line with increased levels of Erfe, we do not observe a decreased expression of BMP ligands, such as BMP2, BMP4, and BMP6, in the skeletal muscle of C26 tumor-bearing mice." (PMID 38052214, 2023). "No obvious change was seen in the expression of BMP2 and BMP6 when the primary tumours developed distant metastases." (PMID 37333824, 2023). "In the current study, we identified the tumor cells as the predominant source of BMP4 in metastasis with ongoing bone formation, while the cell origin of BMP2 was not examined." (PMID 29670000, 2018). "PHD2 is involved in hydroxylation and consequentially degradation of HIF-1α; we found that BMP2 induced increase of PHD2 protein level, in both normal and tumour cells, but this upregulation does not seem to be related to increased protein translation." (PMID 19587783, 2009). "Furthermore, we demonstrated that the downregulation of BMP2 and BMP6 is not tumor-subtype-specific, and the same expression pattern is present across different molecular subtypes." (PMID 38731813, 2024).
cancer (180 papers, 2007 to 2025). A tumor composed of atypical neoplastic, often pleomorphic cells that invade other tissues. "Analysis of the correlation between mRNA expression and CNV from the Genomic Identification of Significant Targets in Cancer revealed that the mRNA expression of BMP2 was associated with shallow deletion, diploidy, and gain in the TCGA database." (PMID 40936753, 2025). "It is important to underline that the expression of BMP-2 in basal-like carcinomas showed a very significant impact on prognosis, as compared to HER2 positive cancers." (PMID 39859358, 2025). "Prior investigations on the effect of BMP-2 use in spine surgery on cancer risk have produced mixed results." (PMID 39392937, 2024). "Five patients were diagnosed with cancer over the course of their follow-up period, but there are several confounding factors that make drawing a causal link between BMP-2 exposure and malignancy difficult in this study." (PMID 39392937, 2024). "Our results are in good agreement with a previous study that observed a marked upregulation of genes associated with cancer stem cells, such as Oct4, Sox2, Nanog, BMP2, and ALDH1, in prostate enzalutamide-resistant cells." (PMID 37958610, 2023). "Unfortunately, BMP-2 is associated with some side effects, including heterotopic bone formation and an increased cancer risk." (PMID 36120459, 2022). "In 2011, researchers applied for recombinant BMP-2 as a new formulation but were rejected due to fears of it as a risk for cancer." (PMID 34956082, 2021). "The cancer risk e.g., was only increased when high doses of BMP-2 were used and by using gene therapy, only low amounts of protein are produced not leading to this increased cancer risk." (PMID 25699253, 2015). "Among the diverse stromal actors, cancer-associated MSCs are determinant for the regulation of CSCs self-renewal via increased expression of BMP-2." (PMID 25303976, 2014). "Once they engraft in ovarian neoplastic microenvironment, cancer-associated MSCs display an expression profile distinct from bone marrow MSCs, with an increased expression of BMP-2, BMP-4 and BMP-6, and a significant downregulation of PDGFRβ and TBX5." (PMID 25303976, 2014). "Specifically, BMP-2 was shown to not only cause G1 arrest of monocultured cancer cells but also reduce the number of cells in S phase and their CDK4 expression." (PMID 25271422, 2014). "During EMT, Bmp2 promotes expression of the basic helix-loop-helix factor Twist1, implicated in EMT in cancer metastases, and the homeobox genes Msx1 and Msx2, indicating that Bmp2 has a crucial role in coordinating multiple aspects of AV canal morphogenesis." (PMID 19424481, 2008). "BMP-2 has been shown to yield positive outcomes in osteogenesis and the healing of spinal injuries; however, its use is contraindicated in patients with a history of cancer, as it has been associated with the promotion of cancer cell proliferation." (PMID 40136878, 2025). "In addition, Carragee et al11 reported a markedly increased risk of cancer in their randomized controlled trial of BMP-2 in posterolateral arthrodesis (OR at 2 years 3.37, 95% CI 1.89-5.56)." (PMID 39392937, 2024). "The use of BMP-2 for clinical purposes arises concerns: the release of rh-BMP-2, especially in surrounding soft tissues, could cause heterotopic ossifications, osteolysis and cancer." (PMID 37092390, 2023). "Thus, a reciprocal loop in which TRAIL from Smad4-deficient CRC cells induces BMP-2 in fibroblasts plays a critical role in cancer progression." (PMID 35693928, 2022). "However, several side effects, including increased risk of developing cancer, have been linked to BMP-2 treatment." (PMID 33772025, 2021). "Nevertheless, the material-loaded BMP-2 may be released in large quantities in a short period of time, which has certain risks, such as swelling, seroma, and even an increased risk of cancer." (PMID 34900969, 2021).
cancer (continued). "Thus, the use of rhBMP-2 raises safety issues regarding cancer risk, but data on the effect of exogenous BMP-2 on cancer are conflicting." (PMID 27636990, 2016). "A controversy exists concerning cancer risk upon BMP-2 administration." (PMID 25699253, 2015). "Bone morphogenetic protein-2 (BMP-2)-containing bone grafts are useful regenerative materials for oral and maxillofacial surgery; however, several invitro and invivo studies previously reported cancer progression-related adverse effects caused by BMP-2." (PMID 25271422, 2014). "The others found cancer risk showing an upward trend after the doctors used a high dose of BMP-2." (PMID 24869484, 2014). "Moreover, patients treated with BMP-2 for posterolateral spinal fusion were found, during follow-up, to have an increased risk of cancer." (PMID 24167632, 2013). "This might indicate the presence of accelerated damage due to the production of inflammatory mediators (e.g. CXCL-16, IL-17, and BMP-2), since high levels of these circulating factors clearly represent a risk for cardiovascular disease, cancer, and metabolic disturbances." (PMID 28293269, 2017). "Increased levels of BMP2 (which drives CSC differentiation toward post-mitotic cancer cells) have been detected in GBM tumors; however, these tumors still retain a subpopulation of pluripotent CSCs, despite high BMP2 expression." (PMID 40277903, 2025). "We found that both EZH2-A and -B subtypes inhibited the expression of these four downstream cancer related genes (BMP2, PRODH, FOXO4, NPRL2), while EZH2-C exhibited the opposite effect." (PMID 39850359, 2025). "So, the Cacna1d, Kcnj12 Tgfb2, Cav1, Mecom, Kitlg, and Bmp2 genes had associations with any of the five pathways of PC1 (glutamatergic synapse, cholinergic synapse, proteoglycans in cancer, pathways in cancer, and MAPK signaling pathway)." (PMID 40076966, 2025). "Another study indicates that BMP2 can stimulate the activation of myeloid-derived suppressor cells and the release of IL-6, thereby promoting the rapid increase in the number of cancer cells and facilitating the progression of liver cancer." (PMID 40136410, 2025). "Studies have shown that BMP2 is a secretory protein highly expressed in various cancers that facilitate cell invasion, metastasis, and EMT." (PMID 38610001, 2024). "Briefly, FSTL1 overexpression stimulates the Wnt/β-catenin pathway to induce tumorigenesis and cancer stem cell maintenance and inhibits the BMP2 pathway, which results in the undifferentiation of cancer cells." (PMID 38672212, 2024). "BMP-2, commonly overexpressed in diverse cancers and tumor cell lines, predominantly contributes to processes such as in metastasis, EMT and invasion, whereas BMP-7 acts as an inhibitor of metastasis in certain cancers like melanoma." (PMID 38660622, 2024). "For instance, previous research has shown that BMP2 stimulation induces the phosphorylation of SMAD1/5 in cancer cells." (PMID 38520036, 2024). "Pre-CAFs exhibited a high expression of genes like PDGFRA, POSTN, BMP2, BMP5, CEBPB, and BICC1, associated with the serrated pathway of CRC and cancer progression." (PMID 39456726, 2024). "Experimental research in the contexts of physiology and pathology has indicated that BMP2 can induce macrophages to differentiate into osteoclasts and accelerate the osteolytic mechanism, aggravating cancer cell bone metastasis." (PMID 39741907, 2024). "INHBC and BMP2 are identified as the growth signals specifically needed by the cancer type, and f2x and f3x are their age-dependent distributions, respectively." (PMID 39796131, 2024). "At the same time, we demonstrated that ECs were transformed into osteoblasts through EndMT after they were treated with CM and BMP-2 protein in this study.Research has suggested the involvement of TG2 in regulating cancer cell autophagy." (PMID 39654623, 2024).
cancer (continued). "Chemokines CCL7, CCL24, and CXCL13, as well as IL-10 and Bmp2, exert pro-tumorigenic effects in a variety of cancers, promoting the invasiveness, metastasis, and stemness of cancer cells." (PMID 38892209, 2024). "Se-Y is an antioxidant with cancer prevention effects, and BMP2, FGF9, and HEY1 are a class of genes associated with the cancer pathway." (PMID 37570275, 2023). "We also evaluated nearby organs such as the heart, liver, kidney, and stomach, and discovered that BMP2-depleted cancer cells reduced metastasis to nearby organs." (PMID 36175474, 2022). "LKB1 mutated tumors having a less suppressive effect on BMP signaling in cancer is suggested by a prior report demonstrating that NSCLC with LKB1 lof had higher expression of BMP2." (PMID 35641992, 2022). "In prostate cancer, decreased BMP-2 expression in cancer tissue is correlated to recurrence and the Gleason score, which represents histological patterns and prognosis." (PMID 35693928, 2022). "BMP2 and BMP4 (BMP2/4) are critically involved in malignant signaling leading to cancer progression and are well-known for their involvement in metastatic and invasive behavior of cancer." (PMID 35902550, 2022). "Large-scale and multicenter cohort studies are needed to draw a scientific conclusion and establish the effects of the BMP-2 on patients living with cancer." (PMID 34869325, 2021). "For example, MSCs increased the population of CSCs by activating the NF-κB signaling pathway through the secretion of IL-6, IL-8, CXCL7, and CXCL12 or BMP2 signaling in various cancers." (PMID 34051847, 2021). "In accordance with this result, BMP2 increased the expressions of mRNA for the cancer stem cell markers CD44 and c-KIT." (PMID 34360647, 2021). "In our previous reports, BMP2 signaling activation has been found to enhance NSCLC bone metastases through enhancing carcinoma cells migration, invasion, osteoclasts differentiation and osteoblasts immature differentiation." (PMID 34136487, 2021). "In the mouse testicular embryonal carcinoma cell line, RA induces Bmp2 while simultaneously repressing Bmp4, specifically through RARα and RARγ." (PMID 34292881, 2021). "TrkB enhances the metastatic potential of cancer cells by promoting cell anchorage-independent growth, migration, and suppressing BMP-2-mediated growth inhibition." (PMID 32731498, 2020). "Analysis revealed that genes associated with cancer stem cells, such as POU5F1 (OCT4), SOX2, NANOG, BMI1, BMP2, CD44, SOX9, and ALDH1 were markedly upregulated in enzalutamide resistant cells." (PMID 33339129, 2020). "BMP2 had been reported to have effects on various cancer attributes, including proliferation, invasiveness, metastatic potential, and angiogenesis." (PMID 32195173, 2020). "Due to these varying reports, it is suggested that use of BMP-2 in the clinic in cancer patients should be carefully considered." (PMID 32933207, 2020). "Another potential way that Mycoplasmas have to influence cancer formation, is by deregulating expression of Bone morphogenetic protein 2 (BMP2), which is an essential growth factor and morphogen, implicated in cancer promotion and growth." (PMID 32899663, 2020). "The findings of these previous studies suggest that BMP-2 expression has potential prognostic value for cancer progression or survival in PCa patients." (PMID 30013089, 2018). "In cancer cells, BMP2 increases cell invasion via PI3K/AKT signaling and induces EMT-like changes in gene expression, such as downregulation of E-cadherin and upregulation of SNAIL or SLUG20,21." (PMID 29416020, 2018). "BMP2 has been reported to increase the mesenchymal adhesion molecule N-cadherin and enhance cell invasion in cancer cells; moreover, studies suggest that N-cadherin promotes placental trophoblast invasion." (PMID 29416020, 2018). "In a study of 46 normal and cancer cell lines, BMP2 was shown to induce SMAD2/3 signaling preferentially in embryonic and transformed cells." (PMID 29416020, 2018).